ATL1 (atlastin GTPase 1)
Diseases named in the same sentence as ATL1 in open-access papers (continued):
Sharing a sentence is not in itself a finding about the gene and the disease.
tumor (8 papers, 2019 to 2025). "By affecting CTGF and CAFs, ATL-1 prevents tumor metastasis and drug resistance, improves TNBC-induced chemoresistance, enhances the therapeutic efficacy of PTX, and provides a new solution for effectively prolonging the survival of TNBC patients." (PMID 38957318, 2024). "In this study, the mechanism of ATL-1 regulating Bcl-2/Bax signaling pathway on tumor cells was investigated." (PMID 36686743, 2022). "To study the role of CTGF in the sensitization of TNBC cells to chemotherapy, we co-cultured TNBC cells and fibroblasts and then examined the effects of ATL-1 and rCTGF on the sensitivity of the tumor cells to paclitaxel by CCK8 assays." (PMID 34692516, 2021). "The data evidence the anti-tumor mechanism of ATL-1, by decreasing the availability of TAM-precursor monocytes and changing TAMs profile in vivo, impairing tumor progression." (PMID 31275860, 2019). "Since lipoxin analog altered the profile of monocyte population derived from bone marrow, it would be possible that ATL-1 would interfere with the ability of these cells to migrate toward the tumor." (PMID 31275860, 2019). "ATL-1 treatment also is able to decreases CD115+LY6Chi monocytes population in the spleen from tumor-bearing mice, when compared to control animals." (PMID 31275860, 2019). "ATL-1 treatment decreased CD206+ TAMs in tumor-bearing mice, contributing for the shift of M2-like TAMs toward an antitumoral profile in vivo." (PMID 31275860, 2019). "Because of that, it was expected that the ATL-1 treatment would diminish monocyte recruitment to the tumor, leading to a reduced TAM cellularity in this microenvironment." (PMID 31275860, 2019). "ATL-1 treatment selectively decreased LY6Chi monocytes population in the bone marrow, in the spleen, and in the blood of tumor-bearing mice." (PMID 31275860, 2019). "ATL-1 inhibited malignant disease of tumor origin and improved survival." (PMID 38957318, 2024). "ATL-1 may promote tumor cell apoptosis and inhibit tumor growth by regulating the expression of related proteins in Bcl-2/Bax signaling pathway." (PMID 36686743, 2022). "ATL-1 can inhibit the proliferation of tumor cells and induce apoptosis in tumor cells." (PMID 34692516, 2021). "However, the antitumor mechanism of ATL-1, especially the specific mechanism by which it increases the sensitivity of tumor cells to chemotherapeutic drugs, is still unclear and requires further study." (PMID 34692516, 2021). "We are the first to find that ATL-1 could affect chemotherapy sensitivity through fibroblasts in the tumor microenvironment." (PMID 34692516, 2021). "In a mouse model, we found that ATL-1 treatments could enhance the chemotherapeutic effect of paclitaxel on tumors and reduce tumor metastasis to the lungs and liver." (PMID 34692516, 2021). "We discovered that ATL-1 could inhibit tumor cell migration and increase the sensitivity of tumor cells to paclitaxel." (PMID 34692516, 2021). "In face of these results, we suggest that ATL-1, together with its ability in inhibiting the angiogenic process, also decreases the availability of TAMs precursor monocytes, able to migrate to the tumor." (PMID 31275860, 2019). "Additionally, ATL-1 is also capable of acting directly on TAMs, altering the M2-like profile of the remaining macrophages in the tumor toward an M1-like cytotoxic profile." (PMID 31275860, 2019). "Besides that, ATL-1 treatment increased the survival rate of tumor-bearing mice that reached more than 80% on the 23rd day after tumor injection and considerably impair the tumor growth." (PMID 31275860, 2019). "In addition to the effect of ATL-1, by decreasing the monocytes that would migrate to the tumor and become TAM, we observed that ATL-1 treatment decreased the weight of spleens of tumor-bearing mice." (PMID 31275860, 2019). "Additionally, ATL-1 treatment induces a in vivo switch in TAMs profile, from M2- to M1-like cells, improving the survival of tumor-bearing mice and decreasing tumor growth." (PMID 31275860, 2019).
tumor (continued). "So we wondered whether ATL-1 could inhibit fibroblast activation in tumor microenvironment." (PMID 34692516, 2021). "We wondered whether ATL-1 could inhibit fibroblast activation via CTGF in tumor microenvironment." (PMID 34692516, 2021). "Thus, ATL-1 actions lead to an impairment of tumor progression." (PMID 31275860, 2019). "Extensive studies using GI cancer models have revealed that AMK compounds, especially ATL-1 and ATL-3, inhibit tumor growth through the TLR4/MyD88 pathways and mitochondrial signaling." (PMID 40144663, 2025). "ATL-1 can inhibit the transformation of fibroblasts into CAFs induced by CTGF and indirectly increase the chemotherapy sensitivity of tumor cells in a co-culture system." (PMID 34692516, 2021). "We observed that ATL-1 showed a specific effect, decreasing the expression of LY6Chi and CD206 on monocyte/macrophage population derived from tumor-bearing mice blood, while increasing these markers on blood monocyte/macrophage from animals without tumors." (PMID 31275860, 2019). "As CTGF and CAF in tumor microenvironment have successfully explained the chemosensitization function of ATL-1 in the following experiments, we did not further examine other genes by RNA-seq at that moment." (PMID 34692516, 2021). "Just reducing the migration ability by ATL-1 may not be sufficient to reduce tumor metastasis in vivo models." (PMID 34692516, 2021). "The results showed that ATL-1 could reduce the production of extracellular vesicles (EVs) and IL-6 secretion by regulating the STAT3/PKM2/SNAP23 pathway, which inhibited aerobic glycolysis and suppressed the ability of tumor cells to induce muscle atrophy, thus alleviating malignant disease." (PMID 38957318, 2024).
cancer (4 papers, 2019 to 2025). A tumor composed of atypical neoplastic, often pleomorphic cells that invade other tissues. "We found that recombinant CTGF (rCTGF) could rescue the downregulation of cancer cell migration by ATL-1 in wound healing assays and Transwell migration assays." (PMID 34692516, 2021). "We found that the expression of CTGF in TNBC cells and fibroblasts could be reduced by ATL-1, which led to a decrease in cancer cell migration and an increase in chemosensitivity." (PMID 34692516, 2021).
neurodegenerative disease (3 papers, 2020 to 2022). A disorder of the central nervous system characterized by gradual and progressive loss of neural tissue and neurologic function. "Mutations in ATL3 and ATL1 have been linked to neurodegenerative diseases, which may be caused by impaired ER-phagy." (PMID 34571977, 2021).
neurological disorders (2 papers, 2016 to 2018). "Because VCP and ATL1 are the causative genes of several neurodegenerative and neurodevelopmental disorders, we suggest that impaired ER formation and inefficient protein synthesis are significant in the pathogenesis of multiple neurological disorders." (PMID 26984393, 2016). "Interestingly, mutations in genes involved in the regulation of ER biogenesis and maintenance, such as Valosin-containing protein (VCP), Atlastin-1 (ATL1), Spastin (SPAST), Reticulon 2 (RTN2), and Receptor expression enhancing protein 1 (REEP1) have been linked to neurological diseases." (PMID 29310658, 2018).
infection (1 paper, 2021). The state of being infected such as from the introduction of a foreign agent such as serum, vaccine, antigenic substance or organism. "In an independent study, it was shown by immunogold-labelling and electron microscopy that one of the Pleiades, Atl1/Ten1, is translocated into maize cells during infection by U. maydis." (PMID 34166468, 2021).
ATL1 also shares sentences with these, for which no sentence is quoted: neuropathy (4 papers); cerebellar ataxia (2); colorectal cancer (2); Dystonia (2); frontotemporal dementia (2); hereditary sensory neuropathy type 1D (2); influenza (2); sensory impairment (2); spinal muscular atrophy (2); Alzheimer disease (1); amyotrophic lateral sclerosis (1); autosomal dominant spastic paraplegia (1); autosomal dominant spastic paraplegia 4 (1); bladder cancer (1); cerebral palsy (1); developmental delay (1); epilepsy (1); epileptic seizures (1); gastric cancer (1); glioma (1); hepatitis C (1); Huntington disease (1); Hyperreflexia (1); intracranial aneurysm (1); leukemia (1); motor neuron degeneration (1); muscle atrophy (1); neurodevelopmental disorder (1); optic atrophy (1); Parkinson disease (1).
A further 6 diseases each share a sentence with ATL1 in 1 paper.